HPSE (heparanase)
Diseases named in the same sentence as HPSE in open-access papers (continued):
Sharing a sentence is not in itself a finding about the gene and the disease.
cancer (continued). "OS-HMW antimetastatic effects have been related to heparanase inhibition and to the ability to lower cancer cell adhesion to endothelial cells, and to intercellular adhesion molecule 1 and P-selectin." (PMID 30413079, 2018). "Collectively, the data presented here support the role of heparanase in multiple biological processes and its involvement in several human diseases beyond cancer." (PMID 30487472, 2018). "It is therefore important to understand how different types of DNA–protein binding complexes influence heparanase expression and affect its involvement in cancer progression." (PMID 29955035, 2018). "Heparan sulfate-mimetics [(i.e., Muparfostat, Roneparstat, Necuparanib, PG545 (= Pixatimod)] that inhibit heparanase enzymatic activity are being evaluated in clinical trials for various types of cancer and appear to be well tolerated." (PMID 29721203, 2018). "The role of HPSE in the development of cancers has been widely investigated and several recent reviews have covered that area in great depth." (PMID 30487472, 2018). "Recent evidence implicates intracellular lysosomal heparanase in the modulation of autophagy, a catabolic pathway maintaining homeostasis in normal cells and dysregulated in several tumors, promoting cancer cell survival." (PMID 30413079, 2018). "The role of HPSE in cancer is mainly due to its HS degrading activity, facilitating cell invasion and metastasis dissemination." (PMID 30487472, 2018). "Heparanase is now well established as a cancer drug target, and several inhibitors have progressed to clinical trials." (PMID 30441818, 2018). "It is known that cancer cells secrete MMPs and other degrading enzymes including heparanase and hyaluronidase which affect components of the EC glycocalyx." (PMID 30546831, 2018). "Heparanase expression is augmented in numerous cancers, including carcinomas, sarcomas, and hematologic malignancies." (PMID 29721203, 2018). "In the following sections, we describe a few examples of cancer-related processes critically regulated by HS and/or heparanase and potential targets of heparin/HS mimetic-based therapies." (PMID 30413079, 2018). "HS mimicking compounds that inhibit heparanase enzymatic activity were examined in numerous preclinical cancer models." (PMID 29721203, 2018). "Heparanase is expressed by most types of cancer and has emerged as a valid target for anti-cancer therapy." (PMID 28359266, 2017). "Interest in HPSE in acute and chronic inflammatory disease and cancer-related inflammation has increased in the last decade and has led to the discovery of novel pro-inflammatory and pro-fibrogenic roles for this enzyme." (PMID 29097791, 2017). "Owing to its unique functionality, studies have suggested important roles for HPSE in cancer metastasis, angiogenesis, inflammation, coagulation and more recently in the stimulation of autophagy and host immune responses." (PMID 28927006, 2017). "Heparanase, therefore, emerges as a potential new target in AP, and heparanase inhibitors, now in phase I/II clinical trials in cancer patients, are hoped to prove beneficial also in AP." (PMID 28386074, 2017). "As a preliminary study, we identified that under hypoxic and nutrient poor conditions, MCF-7 cancer cells released much more mature heparanase in their supernatant than in normal conditions." (PMID 28486399, 2017). "Accumulated evidence indicates that the drugs targeting heparanase reduce angiogenesis, inhibit spontaneous metastasis, and prolong survival in cancer models." (PMID 28505136, 2017). "In most normal cells HPSE expression is low, but it is commonly upregulated in many cancers to promote cell growth, motility, metastasis and inflammation." (PMID 28969075, 2017). "The involvement of heparanase in cancer metastasis is clearly demonstrated in various types of cancer." (PMID 28359266, 2017). "The positive correlation of heparanase with progression of malignancies makes it an attractive target in the treatment of cancer." (PMID 28359266, 2017).
cancer (continued). "Insulin signaling is regarded as a major contributor to this phenomenon; much less is known about the role of heparan sulfate-degrading enzyme heparanase in the link between metabolic disorders and cancer." (PMID 28038446, 2017). "Since TGF‐β is a pluripotent cytokine that can promote or suppress cancer progression and metastasis 29, it is important to elucidate the involvement of heparanase and HS in TGF‐β‐induced signaling and cellular effects." (PMID 28286736, 2017). "The identified lead structure displayed antiproliferative activity and suppressed the migration and invasion of cancer cells in correlation with inhibition of heparanase enzymatic activity." (PMID 28359266, 2017). "PG545, a synthetic fully sulfated HS mimetic with potent, long acting heparanase inhibiting capacity, ended phase I clinical trial in cancer patients." (PMID 28388547, 2017). "From these results, we propose a model where NURF activates Hpse in cancer cells, either directly or indirectly, elevating cell surface heparanase and reducing cell surface HSPGs." (PMID 28969075, 2017). "The surge in interest in heparanase inhibitors over the last decade reflects the recognition within the field that heparanase plays a vital role in cancer pathogenesis and progression." (PMID 26624982, 2016). "To date, the anti-cancer properties of heparins have been attributed to the attenuation of angiogenesis, galectin-3, heparanase and the inhibition of selectins (P- and E-selectin)." (PMID 27602496, 2016). "Heparanase (HPSE), an enzyme that degrades heparan sulfate chains of proteoglycans enriched in endothelial cell layers, is upregulated in many cancers and correlates with metastatic potential." (PMID 27598148, 2016). "While the pro-tumorigenic function of heparanase is well taken, the role of its close homolog, heparanase 2 (Hpa2) in cancer is by far less investigated." (PMID 26968815, 2016). "SSTN peptides that engage VLA-4 or VEGFR2 act as potent inhibitors of this mechanism and have significant potential, along with inhibitors of HPSE enzyme activity, as therapeutics to target cancer and other diseases that depend on this mechanism." (PMID 26926788, 2016). "Heparanase, also recognized as HPSE or HPA1, is another tGLI1 target gene that has been more extensively researched as an antiangiogenic, anti-cancer drug target." (PMID 26891329, 2016). "This is of particular interest, as there are currently four anti-heparanase drugs in clinical trials in cancer patients." (PMID 27408707, 2016). "For its relevance in critical aspects of cancer progression, heparanase represents an attractive therapeutic target." (PMID 27374103, 2016). "Heparanase (HPA) is an enzyme that plays an important role in cancer metastasis and angiogenesis and is a potential target for molecular treatment of tumors." (PMID 27166252, 2016). "Among them there were genes codifying monocyte/macrophage-derived cytokines (IL1β), and matrix related proteins such as Heparanase (HPSE) that have been widely demonstrated to increase microvessel density and reduce survival of cancer patients." (PMID 27281335, 2016). "Studies examining the expression of heparanase in pairs of primary and resulting metastases of other types of cancer are currently ongoing." (PMID 27732945, 2016). "As such, heparanase is considered an attractive target for the development of anti-cancer drugs, and heparanase inhibitors are currently being evaluated in phase I/II clinical trials." (PMID 27732945, 2016). "Several heparanase inhibitors are currently under development and clinical testing in cancer patients." (PMID 27129145, 2016). "PG545 is a fully sulfated, synthetic tetrasaccharide that exerts anti-heparanase activity and has shown promising results against many cancer cells." (PMID 26293675, 2015). "HPSE activity was found to be higher in the malignant neoplasms than in the benign tumors (P<0.0001)." (PMID 26488476, 2015).
cancer (continued). "Many studies have been conducted using tissue samples to investigate the expression of cathepsin B and heparanase isoforms in a variety of cancers." (PMID 25351637, 2015). "SST0001 is a modified heparin with anti-heparanase activity that inhibits cancer cell growth and metastasis." (PMID 26293675, 2015). "Heparanase is an endo-beta-glucuronidase that degrades heparan sulfate chains of proteoglycans and has a multifunctional modulatory effect on cancer cell progression and cell-extracellular matrix interaction." (PMID 25351637, 2015). "Because the ECM provides an essential physical barrier between cells and tissues, heparanase activity has long been correlated with the metastatic potential of cancer cells." (PMID 26569485, 2015). "A literature search for EGR1-responsive genes with roles in cancer and bone identified heparanase, an enzyme that significantly contributes to myeloma bone disease." (PMID 25944690, 2015). "Os resultados demonstraram que as expressões das isoformas de heparanase foram significativamente maiores nas amostras de plasma de pacientes com carcinoma gastrointestinal em comparação com o grupo controle." (PMID 25351637, 2015). "HS extracellular remodeling enzymes, namely heparanase and Sulfs, have increasingly drawn the attention of the cancer pathology and drug development communities." (PMID 25127119, 2014). "Transcriptional patterns of HS-metabolic enzymes (EXT1, EXT2, NDST1, NDST2, GLCE, 3OST1/HS3ST1, SULF1, SULF2, HPSE) were determined in normal, benign, and cancer human prostate tissues and cell lines (PNT2, LNCaP, PC3, DU145)." (PMID 24782989, 2014). "On the other hand, inhibition of expression of heparanase has been reported to have an inhibitory effect on cancer invasion and metastasis." (PMID 25185798, 2014). "The role of heparanase in sustaining the pathology of malignant tumors was confirmed by a variety of reports." (PMID 24632672, 2014). "It presents a potential target for cancer therapies and various molecules have been developed in an attempt to inhibit the enzymatic action of heparanase." (PMID 25295847, 2014). "Heparanase enzymatic activity has been shown to promote the formation of exosomes by several types of cancer cells and, moreover, to affect the molecular composition of the exosomes." (PMID 25105093, 2014). "Immunohistochemistry, in situ hybridization and real time-PCR analyses revealed that heparanase is up-regulated in essentially all major types of human cancer." (PMID 24465803, 2014). "Suppressing heparanase levels as a treatment approach was tested using pre-clinical models in various forms of cancer." (PMID 24887057, 2014). "HPSE2 encodes heparanase 2 which has been implicated as a factor in multiple cancers in humans including UGC and is paralogous to heparanase (HPSE), a well-known oncogene." (PMID 25339718, 2014). "Recently, methylation of heparanase promoter has also been involved in its expression regulation in cancer cell lines." (PMID 24632672, 2014). "It is noteworthy that shed syndecan ectodomain, which can be detected in sampled plasma or serum, represents a potential biomarker for the malignancy status of cancer and its response to a heparanase-targeting therapeutic." (PMID 25105093, 2014). "More recently, pancreatic neuroendocrine tumors (PNET) have now also been identified as a cancer type in which positive heparanase expression was detected in patient tissue samples." (PMID 25105093, 2014). "In 54 tissue samples, cancer samples at late stages (stage IV) showed the highest heparanase expression accomplished by little DNA methylation." (PMID 24632672, 2014). "In summary, this study points to epigenetic control of heparanase expression and cancer phenotype in cell lines, animal models and clinical samples of human via site-specific DNA methylation." (PMID 24632672, 2014).
cancer (continued). "Immunohistochemistry, in situ hybridization, RT-PCR and real time-PCR analyses revealed that heparanase is up-regulated in essentially all human carcinomas examined and in some hematological malignancies (i.e. myeloma)." (PMID 24887057, 2014). "Although HPSE2 activity has not been fully characterized in any species, its antagonistic relationship with HPSE, itself an oncogene, makes it a highly likely protein to influence carcinoma." (PMID 25339718, 2014). "Due to its multiple roles in cancer progression, heparanase is seen as a potential target in cancer treatment." (PMID 23984412, 2013). "The enzymatically inactive form of heparanase has been shown to affect cell signaling, and thus increasing cancer growth with upregulation of several genes expression." (PMID 23516416, 2013). "Stable transfection of the short hairpin RNA construct targeting heparanase TSS (−9/+10 bp) into cancer cells, resulted in decreased proliferation, invasion, metastasis and angiogenesis of cancer cells in vitro and in athymic mice models." (PMID 22363633, 2012). "In the current study, we further demonstrated that TSS-targeted shRNA significantly inhibited heparanase expression and suppressed the invasion, metastasis and angiogenesis of cancer cells in vitro and in vivo." (PMID 22363633, 2012). "Our findings suggest that induction of TGS by TSS-targeted shRNA is a promising approach for the suppression of heparanase gene function as well as illustrating its application in cancer therapy." (PMID 22363633, 2012). "Stable transfection of shP3 (−9/+10 bp) and shCd (+1496/+1515 bp), but not of shP2 (−134/−115 bp) or scrambled shRNA (shScb), resulted in attenuated mRNA and protein levels of heparanase, and decreased in vitro proliferation of cancer cells." (PMID 22363633, 2012). "Due to its important and extensive biological activities, HPSE also plays a critical role in cancer development and progression." (PMID 22952874, 2012). "We detected a considerable inter-individual heterogeneity of paracrine interactions but identified FGF2, HB-EGF, heparanase-1 and SDF1 as factors that were consistently responsible for the activity of carcinoma-associated fibroblasts." (PMID 23056402, 2012). "Utilizing an ELISA method capable of detection and quantification of heparanase, we have recently reported that heparanase levels are elevated in the plasma of pediatric cancer patients, correlating with their response to anticancer treatment." (PMID 21364956, 2011). "A strong parallelism can be proposed with heparanase, an enzyme able to cleave HS chains, generating bioactive fragments and leading to protumorigenic effects in various models of cancer and metastatic processes." (PMID 21599997, 2011). "It is well known that heparanase activity is concerned with angiogenesis, inflammation, and cancer metastasis." (PMID 22133010, 2011). "The limited utility of current angiogenesis inhibitors and the critical need to address the metastatic component of cancer together provide a strong rationale to develop new HPSE inhibitors typified by aglycon-functionalised sulfated oligosaccharides." (PMID 21285983, 2011). "Heparanase, endoglycosidase that cleaves heparan sulfate side chains of heparan sulfate proteoglycans, plays important roles in cancer metastasis, angiogenesis and inflammation." (PMID 20419162, 2010). "Increased expression of the lymphangiogenesis factors and heparanase has been correlated with progressive disease in certain cancers." (PMID 20652010, 2010). "Increased expression of lymphangiogenesis factors VEGF-C/D and heparanase has been correlated with the invasion of cancer." (PMID 20652010, 2010). "Heparanase facilitates the invasion and metastasis of cancer cells, and is over-expressed in many kinds of malignancies." (PMID 20137078, 2010). "On the other hand, the anti-cancer efficacy of the KKDC peptide which inhibits heparanase enzymatic activity is questionable taking into account its pro-adhesive properties." (PMID 18545691, 2008).
cancer (continued). "More recently, heparanase up-regulation was documented in an increasing number of human carcinomas and hematological malignancies." (PMID 18545691, 2008). "Our data again reinforce the importance of HS to the malignant phenotype and highlight the potential therapeutic advantage of targeting heparanase in human cancer." (PMID 17437011, 2007). "Heparanase activity has also been found to correlate with the metastatic potential of various types of cancer cells." (PMID 12087470, 2002). "Beyond cancer, heparanase influences inflammation, autoimmune conditions, and diabetic nephropathy." (PMID 40143176, 2025). "Collectively, we have generated and characterized a novel mAb that specifically neutralizes heparanase enzymatic activity and attenuates its pro-tumorigenic effects in preclinical models, paving the way for its clinical examination against cancer, inflammation, and other diseases." (PMID 40940793, 2025). "Moreover, the secretion of HPSE, an endoglycosidase enzyme produced by both cancer and immune cells, opens straight “highways” for cancer cell invasion and then metastasis by degrading the inter-fiber molecules of HS." (PMID 40643556, 2025). "Heparanase activity directly and indirectly promotes several hallmarks of cancer." (PMID 40940793, 2025). "Given its involvement in multiple aspects of immune cell function, HPSE may also exert beneficial effects in cancer therapy." (PMID 41301515, 2025). "Heparanase enhances not only thrombosis but also inflammation and cancer progression." (PMID 39859197, 2025). "Collectively, we have generated and characterized a mAb that specifically neutralizes the heparanase enzyme and attenuates its pro-tumorigenic effects in preclinical models, paving the way for its clinical examination against cancer, inflammation, and other diseases." (PMID 40940793, 2025). "Therefore, both heparan sulfate and TLR4 activation favor cancer stem-like properties, but active heparanase is essential for the whole process." (PMID 39349458, 2024). "Heparanase is considered a therapeutic target in anti-cancer therapy since it contributes to several processes, which are crucial for cancer progression, such as proliferation, inflammation, extracellular matrix shaping, angiogenesis, resistance to therapy, and dissemination by metastasis." (PMID 39349458, 2024). "We then asked whether heparanase itself was directly responsible for enhanced mammospheres-forming capacity of cancer cells and added the heparanase inhibitor directly to cancer cells." (PMID 39349458, 2024). "Having confirmed that heparanase is essential for mast cell capability to promote cancer cell stem-like features, we hence hypothesized that heparan sulfate could be responsible for the observed effect by TLR4 activation." (PMID 39349458, 2024). "Heparin/HS-mimetics (i.e., Muparfostat = PI-88, Roneparstat = SST0001, Necuparanib = M402, Pixatimod = PG545) that inhibit heparanase enzymatic activity were and are being evaluated in clinical trials for various types of cancer and appear to be well tolerated." (PMID 38334603, 2024). "While heparanase enhances the pathogenesis of cancer, heparanase-2 plays a protective role." (PMID 36980254, 2023). "Furthermore, treatment of BrM cancer cells with astrocyte conditioned media containing heparanase dramatically promoted their migration." (PMID 37728789, 2023). "However, cancer cells can also benefit from the heparanase-1 activity for extravasation and metastasis processes." (PMID 36680276, 2023). "However, dysregulated gene expression in malignant cells leads to overexpression of HPSE in all cancers." (PMID 37297024, 2023). "Intensive research effort in the last two decades conclusively showed that indeed heparanase exerts a strong pro-tumorigenic properties, thus turning heparanase to a valid target for the development of anti-cancer drugs, some of which are under clinical evaluation." (PMID 37491420, 2023).